JAK2 (Janus kinase 2)
Diseases named in the same sentence as JAK2 in open-access papers (continued):
Sharing a sentence is not in itself a finding about the gene and the disease.
colitis (continued). "IL-6/JAK2/STAT3 signaling is a vital axis involved in cell homeostasis and inflammatory signal amplification in various diseases, such as colitis." (PMID 39133435, 2024). "Our research also confirms that XYKJP inhibits IL-6 expression and phosphorylation of JAK2 and STAT3, thereby reducing the inflammatory response to colitis." (PMID 39133435, 2024). "Statistical graphs delineated that the ratios of phospho-JAK2/JAK and phospho-STAT3/STAT3 were lower in the UTI group than those in the colitis group." (PMID 38397811, 2024). "SASP can reduce oxidative stress and the inflammatory response in TNBS-induced colitis model rats by reducing the expression of TNF-α and IL-1β and inhibiting IL-6/JAK2/STAT3 signal transduction." (PMID 39318778, 2024). "Recent findings have indicated that TAK‐242 dose‐dependently alleviated DSS‐induced colitis symptoms and colonic lesions by downregulating TLR4 and JAK2/STAT3 mRNA and protein expression and increasing JAK2/STAT3 phosphorylation." (PMID 38676295, 2024). "In renin transgenic mice, tofacitinib inhibited the phosphorylation of JAK2 and STAT1/3 leading to the attenuation of colitis and better survival." (PMID 37877017, 2023). "Ligliptin activated the AMPK-SIRT1-PGC-1α pathway and inhibited the JAK2/STAT3 signaling pathway, downregulated TNF-α, IL-6 and NF-κB p65, and upregulated the anti-inflammatory cytokine IL-10, reducing the severity of colitis." (PMID 37483618, 2023). "DSS-stimulated colitis rats showed a clear trend of upregulation of p-NF-κB p65, p-STAT3 and p-JAK2 proteins, all of which were downregulated in rats treated with three treatments (P < 0.05,P < 0.01 or P < 0.001)." (PMID 36424592, 2022). "The improved expression of colonic cytokines, JAK2, and STAT3 was closely related to the severity of DSS-induced colitis." (PMID 36312760, 2022). "Consistent with that, the western blotting results showed that phosphorylation levels of JAK2 and STAT3 were significantly increased in DSS-induced colitis mice, and MOP administration reversed this trend." (PMID 35911761, 2022). "Inhibition of JAK2 by AG490 in vivo and in vitro notably hindered the effect of arbutin on the symptoms of colitis." (PMID 34594215, 2021). "In conclusion, arbutin treatment appeared to significantly inhibit JAK2 signal transduction; therefore, it was determined that it played an important protective role in DSS-induced colitis mice." (PMID 34594215, 2021). "Compared with the sham group, the levels of p-JAK2, p-STAT3, and SOCS3 significantly increased in the colitis group." (PMID 34594215, 2021). "The proteins and mRNA of JAK2/STAT3 were significantly upregulated, while phosphorylation of JAK2 and STAT3 was downregulated in DSS-induced colitis mice." (PMID 32762699, 2020). "On the other hand, compared with that observed inwith the control group, the DSS-induced colitis model group had greatly increased mRNA levels of TLR4, JAK2 and STAT3." (PMID 32762699, 2020). "Pretreatment with TAK-242 significantly reduced JAK2/STAT3 protein expression and promoted the phosphorylation of JAK2/STAT3, exerting protective effects on colitis." (PMID 32762699, 2020). "Consistent with previous reports, we observed that TNBS-induced colitis invariably promoted inflammation in the colon with elevated levels of IL-1β, IL-6, TNF-α and an increased expression of JAK2, STAT3, and p-STAT3." (PMID 30042683, 2018). "In addition, hesperetin significantly inhibited the phosphorylation of JAK2 and STAT3 and promoted the expression aof SOCS3, thereby alleviating colitis." (PMID 40078988, 2025). "Our western blot analysis revealed that XYKJP significantly suppressed JAK2 and STAT3 phosphorylation, suggesting that XYKJP's potential therapeutic effects on colitis may be mediated through the inhibition of the JAK2/STAT3 pathway." (PMID 39133435, 2024).
colitis (continued). "We also detected oxidative stress-related biomarkers, inflammatory cytokines, and potential nuclear factor erythroid 2-related factor 2 (Nrf2)/heme oxygenase 1 (HO-1) and janus kinase 2 (JAK2)/signal transducer and activator of transcription 3 (STAT3) pathways in the colitis tissues." (PMID 39133435, 2024). "JAK2 and STAT3 constituted a membrane-to-nucleus signaling module, the phosphorylation of which participates in the expression and biological effect of various inflammatory mediators in colitis." (PMID 38397811, 2024). "Given the phosphorylation inhibition function of SOCS1, we speculated that UTI regulates the JAK2/STAT3/SOCS1 axis to reduce an inflammatory response and barrier impairment in colitis." (PMID 38397811, 2024). "The NF-κB/IL-6/Stat3 and JAK2/Stat3 pathways may be critically involved in CAC tumorigenesis, and it was found that AFE ameliorated colitis and inhibited CAC by downregulating these two inflammation-related signaling pathways." (PMID 38004214, 2023). "An important finding in our study was the decreased phosphorylation of JAK2/STAT3 after NBD combined with FMT treatment, thus suggesting that inhibition of the JAK/STAT pathway might be involved in the anti-colitis effect of combination therapy." (PMID 36424592, 2022). "Moreover, gastric administration of arbutin considerably reversed the expression changes of p-JAK2, p-STAT3, and SOCS3 in colitis." (PMID 34594215, 2021). "Therefore, the activation of IL-6/JAK2/STAT3 pathway is closely related to inhibit the occurrence and development of colitis, which is consistent with the expected results." (PMID 32081954, 2020). "TAK-242 markedly alleviated DSS-induced colitis symptoms and colonic lesions by promoting IL-10 release, inhibiting IL-17 release, downregulating TLR4 and JAK2/STAT3 mRNA and protein expression and increasing JAK2/STAT3 phosphorylation." (PMID 32762699, 2020). "The obtained results indicated that both AG490 and arbutin could alleviate colitis symptoms, downregulate inflammatory indexes, and inhibit the phosphorylation of JAK2 and STAT3 in a mouse colitis model as well as in LPS-induced epithelial and immune cell inflammation models." (PMID 34594215, 2021). "Colitis rats exhibited a remarkable tendency to up-regulate the target proteins (P < 0.05, P < 0.01), while CP could notably lower the levels of pp65, TLR4, p-STAT3, and p-JAK2 (P < 0.05, P < 0.01, P < 0.001)." (PMID 30042683, 2018). "The expression of JAK2 in colitis was not significantly influenced by arbutin and AG490, while the expression of p-JAK2 was significantly suppressed by arbutin and AG490." (PMID 34594215, 2021).
lung adenocarcinoma (40 papers, 2010 to 2025). A carcinoma that arises from the lung and is characterized by the presence of malignant glandular epithelial cells. "Here we show results from a targeted sequencing panel using NCI-MD Case Control Study patient samples and reveal a significantly higher prevalence of PTPRT and JAK2 mutations in lung adenocarcinomas among African Americans compared with European Americans." (PMID 31844068, 2019). "Here, targeted sequencing in African American lung adenocarcinomas finds significantly higher prevalence of PTPRTand JAK2 mutations, validated independently by whole exome sequencing, highlighting potentially clinically actionable mutations in this population." (PMID 31844068, 2019). "Here, we report two genes, PTPRT and JAK2, that are recurrently mutated in lung adenocarcinoma (LUAD) among AAs." (PMID 31844068, 2019). "To further investigate the effects of QSFZYL combined with IFN-γ on the JAK2/STAT3 signaling pathway in lung adenocarcinoma, we performed qPCR analysis for JAK2 and STAT3 in tumor tissues of mice from each intervention group." (PMID 40642092, 2025). "For example, in KRAS-mutated lung adenocarcinoma cells, the secretion of proinflammatory cytokines, including interleukin-6, activates JAK1 and JAK2 through glycoprotein 130 in an autocrine loop, thus, contributing to malignant progression." (PMID 38706597, 2024). "To investigate the potential mechanism by which PRDM5 deregulation promoted the proliferation of lung adenocarcinoma cells, we tested the expression levels of components of the JAK2/STAT3 pathway in A549 cells overexpressing PRDM5." (PMID 36127737, 2023). "Research: Lung adenocarcinoma (LUAD)Achievement: CCT3 promote cisplatin resistance of lung adenocarcinoma (LUAD) cells through the JAK2/STAT3 pathway." (PMID 36185198, 2022). "In lung adenocarcinoma, JAK2/STAT3 activation contributes to EMT and the metastasis of cancer cells." (PMID 35818076, 2022). "UBE alone or in combination with PEM also inhibited the JAK2/STAT3 signaling pathway in lung adenocarcinoma cells." (PMID 35789603, 2022). "Inhibition of STAT3 activity was reported to induce apoptosis in lung adenocarcinoma cells via IL6/JAK2/STAT3 signalling pathway." (PMID 28427199, 2017). "To further validate the effect of JAK2 inhibition on tumor growth in vivo, we performed xenograft assays with HCC-827 lung adenocarcinoma cells, which are driven by an activating mutation (E746-A750 deletion) in EGFR." (PMID 22319590, 2012). "The results above indicated that inhibition of the JAK2/STAT3 pathway triggered by SOCS1 might be mediated by PRDM5 in lung adenocarcinoma cells." (PMID 36127737, 2023). "The overexpression of JAK2 induced the proliferation, migration, and invasion abilities of lung adenocarcinoma A549 cells; conversely, the downregulation of JAK2 could suppress the protumorigenic effect." (PMID 35368663, 2022). "This study showed that treatment with ubenimex alone or combined with pemetrexed could considerably increase the expression level of SOCS1 in patients' serum, lung adenocarcinoma cells, and mouse tumor tissues and inhibit the JAK2/STAT3 signaling pathway." (PMID 35789603, 2022). "We demonstrated that CCT3 could promote cisplatin resistance of lung adenocarcinoma (LUAD) cells through the JAK2/STAT3 pathway." (PMID 34612768, 2021). "Our results indicate IL-6/JAK2/Stat3 pathway also regulates TF expression, which is an important regulator for tumor formation, lung metastasis, and malignant effusion generation in lung adenocarcinoma bearing activated Stat3." (PMID 24086497, 2013).
lung adenocarcinoma (continued). "In this study, we investigated whether IFN-γ-transfected BMSCs combined with QSFZYL affects the progression of lung adenocarcinoma through the JAK2/STAT3 pathway through Western blotting and qPCR analyses of the expression of JAK2/STAT3 pathway-related proteins and genes in intervention groups." (PMID 40642092, 2025). "Besides, Ginsenoside Rh4 could inhibit the metastasis of Lung Adenocarcinoma via suppressing JAK2/STAT3 Signaling pathway." (PMID 38213735, 2024). "In addition, CCT3 downregulation could sensitize lung adenocarcinoma cells to cisplatin by inhibiting the Janus kinase 2/signal transducer and activator of the transcription 3 (JAK2/STAT3) pathway." (PMID 36185198, 2022). "Therefore, in this study, clinical cases and in vitro cell experiments were used to study the effects of lentinan on the proliferation, migration, invasion, apoptosis, and cell stemness of lung adenocarcinoma cells, as well as the involvement of miR-216a-5p and JAK2/STAT3 signaling pathways." (PMID 34900727, 2021). "Previous studies have shown that STEAP1 expression is upregulated in lung adenocarcinoma cells, where it regulates cellular epithelial–mesenchymal transition (EMT) through the (JAK2/STAT3) signaling pathway." (PMID 39991151, 2025). "Meanwhile, IHC analysis was conducted to assess the protein expressions of p-JAK2, p-STAT3, Bcl-2, Snail, and PTPRO in tissue sections obtained from ten cases of clinical lung adenocarcinoma specimens." (PMID 38182570, 2024). "Our study suggests that deregulation of PRDM5 promotes the proliferation of lung adenocarcinoma cells by downregulating SOCS1 and then upregulating the JAK2/STAT3 signaling pathway." (PMID 36127737, 2023). "Our study suggests that the low expression of PRDM5 promotes the proliferation of lung adenocarcinoma cells by downregulating SOCS1 and then upregulating the JAK2/STAT3 signaling pathway." (PMID 36127737, 2023). "According to our results, overexpressed PRDM5 is likely to upregulate the promoter activity of SOCS1 and further suppress the JAK2/STAT3 pathway by inhibiting the phosphorylation of JAK2 and STAT3, thus repressing cell proliferation in lung adenocarcinoma." (PMID 36127737, 2023). "B7-H3-induced signaling includes at least three cascades: PI3K/AKT, JAK2/STAT3, and Raf/MEK/ERK1/2, which are also involved in epidermal growth factor receptor- (EGFR-) triggered signaling in lung adenocarcinoma cells." (PMID 33426073, 2020). "Together, we found that the expression of TF regulated by IL-6/JAK2/Stat3 signaling promotes tumor metastasis and MPE formation in an animal model of lung adenocarcinoma." (PMID 24086497, 2013). "Inhibitors of Jak2/Stat3, MEK/Erk and PI3-K/Akt pathways down-regulated IL-6 secretion in the lung adenocarcinoma PC14PE6/AS2 (AS2) cells, which spontaneously secreted IL-6 and possessed constitutively activated Stat3." (PMID 21122157, 2010). "These suggest that ubenimex combined with pemetrexed in lung adenocarcinoma treatment could be therefore achieved by upregulating SOCS1 expression and then inhibiting the JAK2-STAT3 signaling pathway, further confirming the negative regulatory effect of SOS1 on the JAK2/STAT3 signaling pathway." (PMID 35789603, 2022). "Although CD274 transcription and MHC‐I‐related transcription are both regulated by STAT1 6, 35, MAPK inhibition, in contrast to JAK2 inhibition, does not affect MHC‐I expression, suggesting that MAPK activity primarily regulates CD274 mRNA stability in lung adenocarcinoma cells." (PMID 30972766, 2019).
Sepsis (40 papers, 2013 to 2026). Sepsis is defined as life-threatening organ dysfunction caused by a dysregulated host response to infection. "This demonstrates that the chronic inflammatory state of JAK2 mutant ET predisposes patients to occult sepsis." (PMID 41560006, 2026). "Meanwhile, our findings elucidate the underlying mechanisms of XBJ on sepsis-induced cardiomyocyte apoptosis and inflammation based on NF-κB and JAK2/STAT3 pathways." (PMID 37650558, 2023). "Among 5,607 DEGs, Lrg1, Ace2, Itgb6, Hmgb2, Pik3r5, Itgam, Plcb1, Jak2, Vegfa, and Hif1α were associated with the entire course of sepsis-induced myocardial injury, which have been reported previously." (PMID 35721566, 2022). "The single PMF patient in this cluster was classified as early prefibrotic MF at the time of diagnosis (JAK2-positive with 7% mutated alleles) and died of septicemia 2 years after diagnosis." (PMID 24454890, 2014). "In rat (Rattus norvegicus), the YTHDF1 knock-down macrophages could protect the brain injury and reduce the inflammation caused by severe sepsis via inhibition of JAK2/STAT3 expression." (PMID 37298300, 2023). "In both control and OVR females, sepsis increased the myocardial expression of genes encoding protein associated to inflammation, interleukin-6 (IL-6), IL-10 and IL-18, to cell cycle and survival, Janus Kinase 2 (JAK2) and signal transducer and activator of transcription 3 (STAT3)." (PMID 35322092, 2022). "In the kidney tissue, JAK2 protein expression exhibited a significant increase in the sepsis group compared to the healthy group." (PMID 39955435, 2025). "Curcumin inhibits the activation of the JAK2/STAT3 signaling pathway, suppressing the expression of downstream inflammatory mediators and mitigating tissue damage associated with sepsis." (PMID 41041277, 2025). "In sepsis, the JAK2/STAT3 pathway is specifically induced by IL-6, thereby initiating the proinflammatory effects of this cytokine through the generation of IL-6 trans-signaling." (PMID 39955435, 2025). "Interleukin-6 mediated sepsis-induced muscle atrophy through the gp130/JAK2/STAT3 pathway in a mouse model of sepsis, indicating the possibility of ICU-acquired weakness." (PMID 40708825, 2025). "At the same time, during the development of sepsis, the expressions of JAK2 and STAT3 proteins were significantly up-regulated, and the transcription and expression of downstream inflammatory factors IL-6 and TNF-α were also increased." (PMID 40338919, 2025). "This indicates that the JAK2/STAT3 signaling pathway is involved in the pathogenesis of sepsis and the regulation of inflammation." (PMID 40338919, 2025). "Analysis of kidney tissue revealed that the JAK2/STAT3 signaling pathway exhibited high expression in the sepsis and TCZ16 groups." (PMID 39955435, 2025). "Concurrently, in a sepsis study, Pectolinarigenin mitigate sepsis-induced kidney injury by inhibiting the JAK2/STAT3 pathway." (PMID 39955435, 2025). "Firstly, 44 core targets of sufentanil in the treatment of acute lung injury in sepsis were discovered through network pharmacology, and key targets such as JAK2, SRC and EGFR were screened through PPI network construction." (PMID 39885929, 2024). "Salidroside ameliorate CLP-induced pulmonary fibrosis in mice with acute lung injury from sepsis by downregulating p-JAK2 and p-STAT3 protein expression; also by regulating collagen-related protein." (PMID 38567353, 2024). "Combined with sufentanil’s target protein in acute lung injury induced by sepsis, comprehensive analysis shows that the JAK2/STAT3 signaling pathway is strongly correlated with the application of sufentanil in acute lung injury induced by sepsis." (PMID 39885929, 2024). "Ulinastatin, pterostilbene, Taxifolin and Maresin1 all showed the effect of inhibiting JAK2/STAT3 signaling pathway to reduce inflammation in sepsis and protect lung injury." (PMID 39885929, 2024).